SLC7A11 (solute carrier family 7 member 11)
Diseases named in the same sentence as SLC7A11 in open-access papers (continued):
Sharing a sentence is not in itself a finding about the gene and the disease.
cancer (continued). "We primarily focus on what kind of relationship exists between SLC7A11 and cancer, and how they are connected." (PMID 35804831, 2022). "While clinical data regarding YY2 are still limited, C343R, G317C, and K263N mutations in zinc‐finger domains of YY2 as potentially found in cancer patients cancelled the YY2 regulatory effect on SLC7A11 expression." (PMID 35246964, 2022). "Inhibition of SLC7A11 or GPX4 induces resensitization of radiation-resistant cancer cells to IR-induced ferroptosis, leading to radiosensitization." (PMID 36072803, 2022). "Theoretically, you can always find a way to fight against cancer based on SLC7A11 expression level: restricting cystine or methionine in SLC7A11-low cells, or withdrawal of glucose in SLC7A11-high cells." (PMID 35178349, 2022). "Interferon-γ (IFN-γ) secreted by CD8+ cytotoxic T cells inhibits cystine uptake by cancer cells by downregulating SLC7A11, thus triggering lipid peroxidation and ferroptosis in various tumors." (PMID 36467032, 2022). "Several cancer immunotherapies have been shown to inhibit SLC7A11 function and, in turn, induce ferroptosis in tumor cells." (PMID 35280777, 2022). "Then, focusing on its role in cancer, we describe the relationships of SLC7A11 with tumourigenesis, survival, proliferation, metastasis, and therapeutic resistance in more detail." (PMID 35804831, 2022). "SWI/SNF deficiency inhibits SLC7A11 transcription, impairs cystine uptake and GSH biosynthesis, and promotes lipid peroxidation-induced ferroptosis in cancer cells." (PMID 36552652, 2022). "Thirdly, Although some scholars have proposed initial ideas to target SLC7A11 for cancer treatment, such as directly inhibiting the activity of SLC7A11 transport protein, or starting from the metabolic vulnerability of cancer and SLC7A11." (PMID 35252001, 2022). "And SLC7A11 responded well to ICs in most cancers, particularly the robust performance with PD-L1 in LIHC (p < 0.01)." (PMID 36267158, 2022). "The correlations between SLC7A11 and cancer immune characteristics were analyzed via the TIMER and TISIDB databases." (PMID 35517862, 2022). "Cancer cells further develop the antioxidant systems necessary for oncogene adaption to induce overexpression of SLC7A11, which selectively targets cancer cells while minimizing adverse effects on normal cells." (PMID 36552652, 2022). "According to a Kaplan–Meier (KM) analysis, increased SLC7A11 expression is related to a decreased 5-year survival rate in cancer patients." (PMID 35408533, 2022). "Solute carrier family 7 member 11 (SLC7A11) is a potential target for the chemosensitivity to various drugs in cancer." (PMID 36561981, 2022). "Such metabolic feature confers the cancer cells with elevated expression of SLC7A11 more sensitive to glucose deprivation owing to cystine accumulation-mediated NADPH depletion and impairment of cellular redox homeostasis." (PMID 35053507, 2022). "Combined gemcitabine with ferroptosis inducer erastin increased oxidative stress and lipid peroxidation of cancer cells and decreased the expression level of SLC7A11 protein." (PMID 35915092, 2022). "For example, ubiquitin aldehyde binding 1 (OTUB1) was found to directly interact with and stabilize SLC7A11 in cancer cells." (PMID 35531466, 2022). "Various lines of experimental evidence have shown that genetic or pharmacological inhibition of SLC7A11 has a pro-survival role in cancer cells under conditions of glucose starvation." (PMID 35280777, 2022). "Many studies indicate that several SLC7A11-high cancers are sensitive to glucose deprivation, however the exact mechanism here remains an active area of research." (PMID 35280777, 2022). "The depletion of endogenous OTUB1 reduces SLC7A11 expression and promotes ferroptosis in human cancer cells, which results in growth inhibition of human bladder cancer cell T24 mouse tumor xenografts." (PMID 36551253, 2022).
cancer (continued). "Cancer cells with high SLC7A11 expression take up a large amount of cystine into the cell, and the cell rapidly reduces it to cysteine." (PMID 35804831, 2022). "The upregulation of SLC7A11 was found correlated with a poor response to treatment in different cancers including breast." (PMID 35167614, 2022). "As is previously shown, SLC7A11 overexpression in cancer cells promotes ferroptosis resistance and thus influencing cancer growth, invasion, and metastasis and leads to an unfavorable prognosis." (PMID 34996469, 2022). "Together, our study proposes that KEAP1-NRF2 controls both the SLC7A11-GSH-GPX4 and CoQ-FSP1 arms for ferroptosis defense; consequently, if one arm is disabled, KEAP1 deficient cancer cells can still utilize the other arm to defend against ferroptosis." (PMID 35459868, 2022). "Analysis of 21 different types of cancer in 7462 cancer samples showed that both SLC7A11 and GPX4 are overexpressed in colorectal cancer (CRC)." (PMID 35280777, 2022). "SLC7A11 expressions positively correlate with insensitivity to HDACIs in many types of cancer cell lines." (PMID 36105219, 2022). "Stem cell marker CD44 expression suppresses ferroptosis in cancer cells in an OTUB1-dependent manner by promoting the interaction between SLC7A11 and OTUB1." (PMID 36551253, 2022). "Cancer cells with high SLC7A11 expression are more sensitive to glucose and glutamine restrictions due to their nutrient dependence." (PMID 35804831, 2022). "In cancer cells, Keap1 inactivation promotes ferroptosis resistance following SLC7A11/cysteine/GSH axis activation by stabilizing Nrf2 and Nrf2 target genes." (PMID 36552652, 2022). "We further expand on the role of SLC7A11 in cancer and its potential to serve as a druggable target for anticancer therapy in the following sections." (PMID 35804831, 2022). "SLC7A11-mediated extracellular glutamate secretion can also promote the intrinsic invasiveness of cancer cells." (PMID 36552652, 2022). "We searched the Web of Science database to perform bibliometric analysis, using “SLC7A11” and “Cancer” as search terms." (PMID 35804831, 2022). "As it relates to cysteine, many types of cancers will upregulate SLC7A11, which encodes for xCT, the rate-limiting subunit of the cystine-glutamate antiporter system xC-." (PMID 36276057, 2022). "As the crucial regulator of iron poisoning in cancer cells, SLC7A11 as the crucial regulator of iron poisoning in cancer cells is available to be modulated in the transcription, while declined SLC7A11 is able to stimulate iron poisoning." (PMID 35465835, 2022). "CD44v depletion partially abrogates this interaction, induces SLC7A11 inactivation, and promotes ferroptosis in cancer cells." (PMID 36552652, 2022). "At the same time, we analyzed the ferroptosis key protein SLC7A11 in the TCGA database and found that SLC7A11 is highly expressed in cancer tissues, and its expression is related to the prognosis of patients." (PMID 36008384, 2022). "OTUB1 overexpression is frequently found in various human cancers, which maintains high expression of SLC7A11 in cancer cells by posttranslational regulation of OTUB1." (PMID 36552652, 2022). "The SLC7A11-GSH-GPX4 signaling axis constitutes the major surveillance system to defend against ferroptosis in cancer cells." (PMID 35459868, 2022).
cancer (continued). "As a critical catalytic subunit of system xCT, solute carrier family 7 member 11 (SLC7A11) expression level exhibits an upward trend in multiple cancer types and is an indicator of antiporter xCT activity." (PMID 35884471, 2022). "For validation, we examined the expression of CCL17, CXCL14, and CXCR3 in cancer and adjacent tissues of six patients with SLC7A11 overexpression by ELISA." (PMID 35517862, 2022). "To date, continuing evidence has proven that SLC7A11 is closely related to various aspects of cancer, including tumourigenesis, proliferation, metastasis, prognosis, and chemoresistance." (PMID 35804831, 2022). "As an important source of cysteine necessary for intracellular and extracellular antioxidant activities, SLC7A11 is upregulated in many cancer types in order to alter normal redox homeostasis and mitigate the cytotoxic effects of elevated oxidative stress." (PMID 35326683, 2022). "For cancer cells with high SLC7A11 expression, one therapeutic option is to use SLC7A11-targeted inhibitors—such as SASP—to directly inhibit SLC7A11-mediated cystine uptake and destroy antioxidant defence." (PMID 35804831, 2022). "We analyzed the gene expression changes in SLNs and found that Kcne4 and Slc7a11 were induced in lymphatic endothelium in the early stages of metastasis before cancer cells had metastasized." (PMID 35915077, 2022). "In this study, we identified C8orf76 as a novel SLC7A11 gene regulator at the transcriptional level, which provided new insights into the mechanism of ferroptosis in cancer." (PMID 35884471, 2022). "SLC7A11 is overexpressed in various cancers and suppresses ferroptosis, a type of programmed cell death characterized by the iron-dependent accumulation of lethal lipid ROS, causing the induction of cancer cell growth." (PMID 36499136, 2022). "Transfecting cancer cells (HuH6, HepG2) with the SLC7A11 gene significantly increased cell proliferation and colony formation, and these SLC7A11 knock‐in cells displayed resistance to erastin‐induced ferroptosis, attributable to decreased levels of lipid ROS." (PMID 35604883, 2022). "Many studies indicate that SLC7A11 acts as a key factor in modulating ferroptosis responses in human cancers." (PMID 35399708, 2022). "In terms of mechanism, CD8 + T cells can down-regulate the expression of SLC3A2 and SLC7A11 by releasing IFNγ, thereby reducing the uptake of cystine and promoting lipid peroxidation in cancer cells." (PMID 34996454, 2022). "OTUB1 (OTU deubiquitinase, ubiquitin aldehyde binding 1), which is overexpressed in a variety of human cancers, was shown to function as a major regulator for SLC7A11 stability." (PMID 35307036, 2022). "Upregulation of SLC7A11 in cancers is needed to adapt to high oxidative stress microenvironments and maintain cellular redox homeostasis." (PMID 36552652, 2022). "BAP1 represses SLC7A11 expression by decreasing H2Aub occupancy on the SLC7A11 promoter in many cancers." (PMID 35847989, 2022). "One related nutrient transporter to this process that is frequently overexpressed in human cancers is the cystine/glutamate antiporter solute carrier family 7 member 11 (SLC7A11)." (PMID 35448878, 2022). "For antioxidant metabolism, overexpression of the cancer stem cell marker CD44 enhances the stability of SLC7A11, a key regulator of lipid peroxidation, and inhibits ferroptosis in cancer cells." (PMID 34784264, 2022). "We have demonstrated that in the presence of enzalutamide or darolutamide, AR is enriched in the distal elements of cancer-related genes such as NR3C1 (encoding GR) and SLC7A11, and upregulates their expression in both ADPC and CPRC cell models." (PMID 35864113, 2022).
cancer (continued). "Cancer cells’ ability to manage oxidative stress is possible due to the presence of the xCT (also known as SLC7A11), a functional subunit of the cystine/glutamate antiporter system xc-." (PMID 36362074, 2022). "It has been demonstrated the role of BAP1 in attenuating cancer development by provoking the ferroptosis event via solute carrier family 7-member 11 (SLC7A11) inhibition." (PMID 35205167, 2022). "It has been shown that the FDA-approved drugs sulfasalazine and sorafenib both have radiosensitising effects on cancer cells, likely through their actions on SLC7A11." (PMID 36314903, 2022). "SLC7A11 mediated cellular uptake of L-alanosine in cancer cells and conferred chemoresistance to geldanamycin by supplying cystine for GSH biosynthesis." (PMID 36552652, 2022). "Here, the authors show that BCSCs secrete DKK1 to protect metastasizing cancer cells from ferroptosis via upregulation of SLC7A11, and further show that the combination of a ferroptosis inducer with a DKK1 inhibitor reduces metastasis." (PMID 35296660, 2022). "Even after chemotherapy or radiotherapy, some cancer cells upregulate the expression of SLC7A11 to resist oxidative stress, inhibit cell death, and develop treatment resistance." (PMID 36552652, 2022). "For instance, suppression of the SLC7A11 gene results in re-sensitization of CSCs when treated with cold plasma, method for cancer treatment that works by elevating the intracellular ROS production." (PMID 35566360, 2022). "Subsequently, the correlation between SLC7A11 and the expressions of immunoinhibitors (or immunostimulators) in different cancers were analyzed." (PMID 35517862, 2022). "Cystine/glutamate exchanger (xCT) is an important molecule mediating ferroptosis resistance in cancer cells, which is comprised of SLC7A11 and SLC3A2." (PMID 35992269, 2022). "SLC7A11 is a core target-regulating ferroptosis, and its overexpression leads to downregulation of the sensitivity of cancer cells to ferroptosis." (PMID 35517862, 2022). "The utilization of SLC7A11 to uptake Sec instead of cysteine facilitates the synthesis of selenoprotein GPX4 by cancer cells." (PMID 36358931, 2022). "The xCT (encoded by SLC7A11) is a functional subunit of glutamate antiporter system Xc− and is overexpressed in many cancers." (PMID 36320056, 2022). "The crosstalk between SLC7A11 and other 32 malignancies with pan-cancer analysis revealed that SLC7A11 showed positive correlations with multiple ICs in most cancer types, but it also predicted a high risk of adverse outcomes in several cancers." (PMID 36267158, 2022). "Other authors have proposed that cancer cells require large amounts of energy substrates to maintain a strong antioxidant defence system through SLC7A11, resulting in glucose and glutamine dependence." (PMID 35804831, 2022). "The distinct anticancer effect of SLC7A11–GSH axis blocking has been established in various human cancers." (PMID 36552652, 2022). "As an essential ferroptosis repressor, slc7a11 was overexpressed in some cancer tissues and contributed to cancer growth." (PMID 35773623, 2022). "Nevertheless, a high degree of complexity has emerged regarding the role of SLC7A11 in cancer, with clear discrepancies between pro- and antitumourigenic activities evident when utilising cell culture versus in vivo models of malignancy." (PMID 35804831, 2022). "Cancer cells import a large amount of cystine into the cell through high levels of SLC7A11 expression (SLC7A11high) and quickly reduce highly insoluble cystine to more soluble cysteine." (PMID 36552652, 2022). "Although SLC7A11 is overexpressed in various cancers, cancer cells maintain redox homeostasis by developing different antioxidant defenses to survive high levels of oxidative stress." (PMID 36552652, 2022). "SLC7A11 overexpression is found in many human cancers and is highly sensitive to selective inhibition of SLC7A11." (PMID 36552652, 2022).
cancer (continued). "We found that SLC7A11 expression was up-regulated by selenite in all cancer cell lines tested either in glucose replete or condition of starvation." (PMID 35053507, 2022). "DKK1 increases the expression of SLC7A11 to protect metastasizing cancer cells from lipid peroxidation and ferroptosis." (PMID 35296660, 2022). "Mechanistically, we found that SLC7A11 expression in cancer cells was up-regulated by selenite both in vitro and in vivo." (PMID 35053507, 2022). "While the role of SLC7A11 in cancer biology has been studied widely in recent years, few studies have focused on the effect of SLC3A2 during tumorigenesis and its association with patients’ prognosis." (PMID 35992269, 2022). "To analyze the changes that occur in LNs before cancer cell metastasis, we analyzed the gene expression changes of SLNs in the early stages of metastasis in our model and found that Kcne4 and Slc7a11 were increased." (PMID 35915077, 2022). "Sometimes, these ncRNAs can directly target GPX4, SLC3A2 and SLC7A11 to induce ferroptosis in cancer cells." (PMID 35342359, 2022). "Cancer cell exhibits ability to evade ferroptosis by activation of antioxidant signaling pathways such as SLC7A11/GPX4 axis." (PMID 36289191, 2022). "High basal ROS levels and SLC7A11 dependences in cancer cells render them vulnerable to further oxidative stress." (PMID 36552652, 2022). "Inactivation of SLC7A11 or GPX4 with ferroptosis inducers is able to sensitize radioresistant cancer cells and xenograft tumors to IR." (PMID 35847022, 2022). "Many therapeutic approaches have been demonstrated in preclinical models to modulate the activity or expression of SLC7A11 in cancer." (PMID 35804831, 2022). "Despite this apparent dependence of cells on system xc−, animals with knockout of the slc7a11 gene are fertile and develop completely normally, which prompted the consideration of SLC7A11 inhibition as an eventual cancer therapy with few adverse effects." (PMID 35898880, 2022). "This suggests that cellular ROS following glucose deprivation plays a critical role in SLC7A11-dependent cancer cell death." (PMID 36552652, 2022). "Another fascinating topic in SLC7A11 research in recent years has been to uncover the role of SLC7A11 in inducing nutrient dependency in cancer cells." (PMID 33000412, 2021). "Later, emerging studies reveal that under various cellular stresses in a host of cancers, SLC7A11 is mostly adaptively upregulated to mitigate intracellular ROS and replenish GSH, thereby antagonizing cell death and resisting anticancer therapies." (PMID 34722314, 2021). "Based on the pan-cancer analyses using the StarBase tool that includes 32 tumors types, the ceRNA analyses of SLC7A11 with 109 genes in the “autophagy-animal” pathway (map04140) was systematically analyzed." (PMID 34790572, 2021). "Since glutamine is a good substrate for SLC6A14 and SLC38A5, the Na+-coupled concentrative influx of these amino acids into cancer cells is likely to activate the heterodimeric amino acid transporter known as cystine/glutamate exchanger (SLC7A11/4F2hc)." (PMID 33806675, 2021). "SLC7A11 transcript levels were also decreased with both ATF4 knockdown and rapamycin in the PTEN-deficient cancer cell lines LNCaP and PC3, although SLC7A11 expression was relatively more resistant to rapamycin in PC3 cells." (PMID 33646118, 2021). "Among the various functions of SLC7A11, Recent years, involvement of SLC7A11 in metabolism and ferroptosis of cancer cells has gained great attention." (PMID 34177591, 2021).